MUC16 (mucin 16, cell surface associated)
Diseases named in the same sentence as MUC16 in open-access papers (continued):
Sharing a sentence is not in itself a finding about the gene and the disease.
tumor (continued). "For example, REGN4018 targeting MUC16/CD3 and MUC16/CD28 targeting MUC16 are both bispecific antibodies binding to MUC16 proximal membrane region (MUC16△), which can effectively bind MUC16 and induce T cells to redirect to kill tumor cells." (PMID 38758220, 2024). "MUC4, MUC16, and MUC17 were found in most tumor samples ( > 78%)." (PMID 38637560, 2024). "The upregulated expression of Muc16 on tumor cells contributes to both the metastasis and progression of disease in multiple malignancies, including PDAC,8,26 which underscores the decreased survival observed in patients with high Muc16 gene expression." (PMID 39346763, 2024). "Adhesion among tumor cells, mesothelial monolayers, and ECM components is achieved through interactions between integrins, cadherins, and cell adhesion molecules, including integrin α2β1, proteoglycan CD44, and mucin 16 (MUC16)." (PMID 37377954, 2023). "Due to low pure fractions of MUC16-expressing mesothelial cells in PDAC tissues when compared to the normal pancreas, we hypothesized that Tumor Microenvironment (TME) influences MUC16 expression and mesothelial cell identity." (PMID 36816942, 2023). "Similarly, MUC16-overexpressing TCGA-PAAD tumors also registered poor on a few clinico-pathological scales (fraction of genome altered, neoplasm status, tumor resected maximum dimension, and survival)." (PMID 36816942, 2023). "Besides its tumor-promoting role in CRC, elevated MUC16 has been reported to promote metastasis and, therefore, is considered a marker for the evaluation of metastasis in CRC patients." (PMID 36980526, 2023). "Further, the tumor tissues of MUC16 whole-body knockout (KPCM) showed dysregulation in the markers of actomyosin assembly and fibroblast differentiation (iCAF and myCAF), indicating that MUC16 has an extra-tumoral role in controlling CAF differentiation." (PMID 36816942, 2023). "Likewise, several reports allude to MUC16 and N-cadherin-mediated acquisition of EMT phenotype and tumor progression in NSCLC18,51." (PMID 37567918, 2023). "In our study, MUC16 induced high expression of immunosuppressive factors such as IL-6, IL-8, PD-L1 and IDO1 in neutrophils, which might result in the weakness of tumor cell-killing ability for NK cells." (PMID 37644468, 2023). "The specificity of tumor uptake was validated by imaging and biodistribution studies of mice bearing MUC16-negative SKOV3 xenografts." (PMID 36559316, 2022). "Several aspects need to be discussed as potential cofactors for the negative impact of MUC16 (+) on survival, i.e., MUC16 (+) patients had higher Pn status, more frequently positive serum levels of tumor marker CA-19/9, and increased Ki-67 proliferative index." (PMID 36230626, 2022). "For the other three genes (MUC16, PAX8 and SOX17) in combination, their RNA quantity may distinguish OSCA from other 29 tumor types." (PMID 35954427, 2022). "Specific tumor uptake was observed for SW1990/OVCAR3 xenografts but not in MUC16-negative SKOV3 xenografts." (PMID 36559316, 2022). "Finally, other proteins identified in our 4 × 4 proteomic comparison of PDAC vs HC organoid EVs with more variability in the larger PDAC panel (PTPRJ, MUC16, TAOK1) are also reported markers of tumor-development in several cancer models." (PMID 35241737, 2022). "Previous studies have suggested that HCC tumor cells did not produce mucin, but the latest research proved that tumor cells can produce mucins such as MUC16 in HCC with bile duct differentiation." (PMID 33867349, 2021). "Employing an unbiased immunopeptidome analysis of tumor specimens derived from 35 PDAC patients, VGLL1 was identified as a putative shared TAA, ranked second only to MUC16 in terms of tumor expression in comparison to essential normal tissues." (PMID 33087697, 2020). "Tumours derived from the MUC16 knockdown cells were either not detectable or significantly smaller (p < 0.0001)." (PMID 33322519, 2020).
tumor (continued). "The tumor markers MUC1 and MUC16 were identified as glycoproteins carrying the Tn cluster." (PMID 33019700, 2020). "However, a considerably stronger tumor-cell-specificity for SPINT2 was observed compared to WFDC2 and MUC16." (PMID 31737572, 2019). "MUC4, MUC16 and MUC20 mRNA expression was evaluated in datasets to analyze whether the mRNA level differed between normal and tumor tissues." (PMID 30236127, 2018). "Tumor uptake between the antibodies was generally not significantly different despite the high lymphoid uptake of 89Zr- MUC16-CD3high." (PMID 30400822, 2018). "Indeed, overexpressed broad spectrum or specific sialic acid-containing ligands (e.g., MUC16, GD3, GD2, GT1b, etc.)are reported to be responsible for the impaired immune status in tumor microenvironment and serves as prognostic markers and therapy targets." (PMID 29899741, 2018). "MUC16 and MUC20 mRNA level were also increased (p < 0.0001 and p = 0.0062) in tumor samples." (PMID 30236127, 2018). "Expression of both MUC16 and MUC1 has also been shown to dampen the Toll-like receptor mediated immune response at ocular surfaces, and may play a role in tumor progression." (PMID 27483328, 2016). "The most studied molecules in tumour cell adhesion are integrin α2β1, CD44 s and MUC16." (PMID 27074785, 2016). "Following attachment to the tumor via surface bound MUC16, Meso-TR3 acquires full activation with superior killing profiles compared to non-targeted TR3, while its bioactivity is substantially reduced on cells that lack the tumor marker." (PMID 24447304, 2014). "Furthermore, MUC16 suppresses natural killer (NK) cell-induced cytolysis in EOC patients, indicating that it compromises immune-mediated tumor surveillance and destruction." (PMID 22481932, 2012). "The scFv-MUC16 complex is rapidly degraded in the proteasomes and the mucin does not accumulate in the cytoplasm of the tumor cells." (PMID 20089172, 2010). "The mechanism regulating the production and/or secretion of mucin MUC16, which is recognized by the OC125 antibody, is as yet unknown, and it could potentially be altered by biochemical modulation of the tumor." (PMID 20072701, 2010). "Importantly, MUC16 + SKOV3 or Raji tumor cells express negligible levels of SIRPα and do not function as an antigen sink for these antibodies." (PMID 40408355, 2025). "We hypothesized that EMT transition and downregulation of the MUC16/CA125 target could be a potential mechanism of resistance in these cells; indeed, we found decreased CA125 expression in both M02 and M10 tumor cells despite clinically increased CA125 in both patients." (PMID 41413213, 2025). "Notably, MUC16 expression stands out in NSCLC, significantly elevated compared to adjacent non-cancerous tissues, and tightly correlated with clinicopathological parameters like tumor staging, pathological grading, and lymph node involvement." (PMID 40655139, 2025). "In addition to tumor foci, some benign ducts and ampulla regions expressed MUC16 in the matched adjacent tissue (NCT: 13.3%, M = 2.75; non-NCT: 17.9%, M = 3.8)." (PMID 39456534, 2024). "In our samples, the surrounding benign or precancerous tissue matched to the NCT or non-NCT samples minimally expressed MUC16, indicating that high tumor-to-background ratios and tissue differentiation may be achievable in PDAC." (PMID 39456534, 2024). "Besides, it has also been found that the MUC16 CTD could increase the degradation of β-catenin by interacting with β-catenin to enhance the formation of multicellular aggregates, which promotes tumor progression in EOC." (PMID 30795761, 2019). "However, tumor recurrences at early time points from mice treated with TAG72-BBζ CAR T cells showed a dramatic reduction in TAG72 expression, while maintaining expression of MUC16 and MUC1." (PMID 30510550, 2018).
tumor (continued). "More specifically, by taking advantage of the high affinity interaction between mesothelin and MUC16, we recently designed a mesothelin/TR3 fusion protein, designated Meso-TR3, in order to tether our therapeutic to the MUC16 biomarker located on the tumor cell membrane." (PMID 27120790, 2016). "Incorporation of the purified protein (e.g., MUC16 or PODXL) into a lipid bilayer allows for its physiologically relevant orientation and provides a consistent binding interface, while eliminating the potential contribution of other selectin ligands present on the tumor cell surface." (PMID 26329844, 2015). "However, whether MUC16 mutations are associated with TMB and tumor-infiltrating immune cells in LUAD is not fully elucidated." (PMID 37932988, 2023). "MUC16 cDNA mutations patterns showed that the presence of ENST00000397910.8:c.12272T>A and ENST00000397910.8:c.12143G>A together persisted frequently in the tumour samples (four out of seven samples) but not in the margin tissue samples (one out of eight samples)." (PMID 37504272, 2023). "However, the tumour‐promoting mechanism of MUC16 is not entirely clear." (PMID 33543559, 2021). "MUC16 may be expressed by various tumor cell types and by some normal epithelial cells." (PMID 31039761, 2019). "After initial characterization of the glycosylation of MUC16, there has not been a robust and systematic characterization of the glycan chains attached to each domain of the mucin or of the glycan site occupancy in mucin molecules produced by tumor versus normal epithelial cells." (PMID 24886523, 2014). "Neither tissue showed appreciable expression of HER2 or MUC16; however, both displayed levels of CD24 that were detectable yet significantly below those evident in the tumor samples." (PMID 40841152, 2025). "The HIO factor MUC16/CA125 binding to SS1 ADC was shown to have a negative effect on internalization and tumor cell killing." (PMID 37195923, 2023). "The MUC16/CA125 refractory NAV-001 ADC was shown to have robust killing of MUC16/CA125 expressing and non-expressing tumor cells in vitro and in vivo at single, sub-mg/kg dosing." (PMID 37195923, 2023). "In conclusion, we developed a new Nb targeting MSLN, regardless of the presence of its ligand MUC16, and used it successfully to detect MSLN-positive tumours in vivo." (PMID 37388728, 2023). "In both the OVCAR3 and OV90 models, tumor recurrences at early time points following CAR T cell treatment were TAG72 low/negative, but maintained MUC16 and/or MUC1 expression." (PMID 30510550, 2018). "In all, 31 matched adjacent tissues showed a decrease in MUC16 expression (54.4%) (NCT and non-NCT: M = 7.02; matched adjacent: M = 1), and 10 increased in MUC16 expression (17.5%) (NCT and non-NCT: M = 1.5; matched adjacent: M = 5.3) compared to the matched NCT or non-NCT primary tumor tissue." (PMID 39456534, 2024). "It is believed (but not proven) that MUC16 undergoes cleavage in the penultimate SEA domain to generate circulating CA125, which is well known for its application as a clinical biomarker for the diagnosis of tumor recurrence, especially for EOC." (PMID 30795761, 2019). "For example, OVCAR8 (derived from primary tumour in the ovary), SKOV3 (derived from ascitic fluid) and EFO27 (derived from omentum metastasis) presented the same immunophenotype without expression of MUC16, MUC1, Tn, STn, and T." (PMID 30011875, 2018). "As an example, MUC16 expression has been detected in various pancreatic cell lines derived from metastasis (Capan1, Colo 357, T3M4), meanwhile its expression was negative in Panc-1 cell line, derived from primary tumor." (PMID 28704462, 2017).
cancer (453 papers, 1998 to 2026). A tumor composed of atypical neoplastic, often pleomorphic cells that invade other tissues. "MUC16 is a tumor-associated antigen expressed on the surface of cancer cells, making it a compelling target for ADCs designed to deliver potent cytotoxic agents directly to these tumors." (PMID 41347223, 2025). "MUC16 ranks among the top three genes exhibiting the highest mutation frequencies in various cancer types." (PMID 40478193, 2025). "Epitope CA125 in Mucin-16 (MUC16) is a well-known diagnostic marker of various cancers, including ovarian and pancreas cancer." (PMID 40149293, 2025). "Reports demonstrated high-frequently mutations in TNN and MUC16 had better prognosis and immunotherapy efficacy than patients with the low-frequently mutations or the wild-type genes in cancer patients." (PMID 40066453, 2025). "Other genes reported as cancer related in COSMIC (v98) showing high proportions of shared non-synonymous mutations were MUC16 (10 patients), FAT4 (6 patients) and CDKN2A (7 patients)." (PMID 39020404, 2024). "In recent years, MUC16 mutations have gradually been found to be a marker for the early identification of cancer." (PMID 38758220, 2024). "CA-125, alternatively known as mucin 16 or MUC16, denotes a protein encoded by the MUC16 gene and exhibits elevated levels in specific cancer types, notably ovarian cancer." (PMID 38939264, 2024). "Our study is the first in Thai patients to draw a comprehensive mutational landscape of somatic mutations and identify frequently mutated genes, such as MUC4 and MUC16, with significant cancer driver alterations." (PMID 39338204, 2024). "Although a reduction in MUC16 has previously been associated with certain types of cancer, further studies are needed to elucidate the role of MUC16 on VF." (PMID 38473795, 2024). "Recent studies have found that MMP13 (Matrix Metallopeptidase 13) and MUC16 (Mucin 16) are significantly more frequently mutated in LoY across various cancer types." (PMID 39594721, 2024). "Previous research has indicated a correlation between mutations in TTN and increased responsiveness to ICI therapy in solid tumors, while MUC16 mutations are linked to cancer advancement and prognosis." (PMID 38707466, 2024). "Using the Cancer Genome Interpreter, we identified five recurrent cancer driver mutations spanning MUC16, MUC4, ALK, and CTNND1, with the latter being novel and containing a missense mutation, R439C." (PMID 39338204, 2024). "Studies have demonstrated that MUC16 mutations are also associated with increased cancer cell growth and metastasis." (PMID 38956143, 2024). "While MUC16 plays a protective role in healthy physiology, it has been implicated in disease progression and metastasis in various cancers." (PMID 37730831, 2023). "The clinical utility of MUC16 as a diagnostic aid for risk stratification, early detection, and differential diagnosis is still relevant to contemporary cancer diagnostics." (PMID 36816942, 2023). "Cancer antigen 125/Mucin 16 (CA125/MUC16) has been associated with cancer progression and metastasis in various cancer types, including breast cancer." (PMID 36918912, 2023). "It was shown that nine out of nineteen mucin genes (including MUC6 and MUC16) were frequently mutated in various cancer types, including HNSCC." (PMID 37504272, 2023). "Some studies suggest an association between mutations in MUC16 and the immune response and the cell cycle in cancer patients." (PMID 37504272, 2023). "Next, we aimed to delineate the underlying molecular mechanism of anti-MUC16 antibody-mediated inhibition of cancer progression and metastasis in PC and NSCLC." (PMID 37567918, 2023). "It is known that the mucin 16 (MUC16) mutation is the most common and affects the progression and prognosis of several cancers." (PMID 37932988, 2023).
cancer (continued). "MUC16 was considered one of three genes with the greatest frequency of mutations across a variety of cancers." (PMID 36552994, 2022). "CA125, also known as MUC16, is a glycoprotein antigen of transmembrane mucin that is associated with many malignant tumors with poorer prognosis." (PMID 35719995, 2022). "Among these, MUC16 is often mutated in different kinds of human cancer and has been linked to increased cancer cell proliferation." (PMID 36231045, 2022). "We decided to focus on CTNNB1 and MUC16, which are recognized as being associated with cancer, for a further investigation." (PMID 36199046, 2022). "Keeping with these findings, Galectin-1 and MUC16 have been associated with EMT in different kinds of cancer, including PDAC18–20." (PMID 35017635, 2022). "For example, mucin 16 (Muc16) is a surface-associated mucin that contains a known cancer antigen (Ca125) within its protein sequence and is highly expressed ectopically on OvCa cells." (PMID 33810259, 2021). "For example, MUC16 (CA-125) is a very long protein (14,500 amino acids), which is easier to mutate in cancer cells." (PMID 33579226, 2021). "MUC16 variants have frequently been reported in most cancer types but considering the long coding sequence of this gene, the mutational heterogeneity of MUC16 is not elevated in BC." (PMID 34001236, 2021). "MUC16, encoding a type I transmembrane mucin protein, is frequently mutated in multiple types of human cancer." (PMID 34540650, 2021). "For example, MUC16 is highly predictive of 15 cancer types, but only if its mutations are synonymous." (PMID 34385450, 2021). "Among them, MUC1 and MUC16 were found to be associated with immune modulation and metastasis in cancer." (PMID 34327857, 2021). "Unsurprisingly, the most frequently mutated matrisome genes across the Pan-Cancer cohort —namely mucin 16 (MUC16) and filaggrin (FLG)—top the list of PTMmut-affected genes too." (PMID 33802493, 2021). "The differences in mean expression levels of these genes in MUC16-mutated vs wild-type tumors from the respective cancer types are presented in eFigure 4 in the Supplement." (PMID 32845327, 2020). "The expression of cancer antigen-125 (CA-125), encoded by the MUC16 gene, is upregulated in various cancers." (PMID 32513981, 2020). "MUC16 encodes a repeating peptide epitope of mucin that promotes cancer cell proliferation and inhibits anti-cancer immune responses." (PMID 33173439, 2020). "Our analysis of the TCGA pan-cancer data set across multiple solid tumor types demonstrated that MUC16 mutation was associated with factors previously associated with response to ICI therapy." (PMID 32845327, 2020). "MUC16 also has a high mutational rate in cancers, and amino acid‐altering mutations were observed in 43% of PC specimens, with 14.9% leading to deletions or frameshifts." (PMID 32745356, 2020). "MUC16 variants were found to induce MUC16 overexpression in BC and thus caused increased cancer growth and migration as well as decreased sensitivity to cisplatin." (PMID 31254045, 2020). "MUC16 variants were reported to be frequently found in most cancer types which is in line with the high prevalence of MUC16 variants in our patient cohort." (PMID 31254045, 2020). "Cell surface-associated Mucin 16 (MUC16) is used as a marker for different cancers and associated with an ovarian cyst." (PMID 31272500, 2019). "Among these oncogenic genes, MUC16 encodes a repeating peptide epitope of mucin that promotes cancer cell proliferation and inhibits anti-cancer immune responses." (PMID 30786925, 2019). "MUC1, MUC2, MUC4, and MUC16 are mucins associated with cancer progression, whereas MUC16 is also used for cancer diagnostics." (PMID 31552050, 2019). "Due to the high-molecular-weight, all previous studies of MUC16 only used knockdown (KD) technology to study MUC16 deficiency in cancer." (PMID 30795761, 2019).